GLO1 (glyoxalase I)
Diseases named in the same sentence as GLO1 in open-access papers (continued):
Sharing a sentence is not in itself a finding about the gene and the disease.
endothelial dysfunction (16 papers, 2014 to 2025). In vascular diseases, endothelial dysfunction is a systemic pathological state of the endothelium (the inner lining of blood vessels) and can be broadly defined as an imbalance between vasodilating and vasoconstricting substances produced by (or acting on) the endothelium. "Given findings that GLO1 mitigates aging-associated endothelial dysfunction, which causes CVD in the long term, regulation of glycative stress may represent a versatile target for the prevention of vascular aging and CVD." (PMID 24612481, 2014). "Glyoxylase 1 (Glo1) is rate-limiting for this process, and mice with genetic overexpression of Glo1 are protected from renal, retinal, and endothelial dysfunction and damage when rendered diabetic." (PMID 36135209, 2022). "Overexpression of GLO1 in diabetic rats reduced the production of AGEs, endothelial dysfunction, and also expression of early markers of kidney damage." (PMID 29783710, 2018). "Age-related aortic glycative stress, the subsequent inhibitory phosphorylation of endothelial NO synthase (eNOS) (Thr495), and endothelial dysfunction were alleviated by GLO-1 over-expression." (PMID 28106734, 2017). "Together, GLO1 reduced age-related endothelial glycative and oxidative stress, altered phohphorylation of eNOS, and attenuated endothelial dysfunction." (PMID 24612481, 2014). "Importantly, we further demonstrated using GLO1 systemic overexpression model rats that regulation of glycative stress prevents these age-associated changes, namely vascular glycative and oxidative stress, glycation and carbonylation of proteins, eNOS phosphorylation, and endothelial dysfunction." (PMID 24612481, 2014). "In addition, age-related glycative and oxidative stress, resulting in endothelial dysfunction, is reduced in Glo1 transgenic rats." (PMID 28106778, 2017). "Therefore, it is highly likely that GLO1 activates eNOS by attenuating age-related increase in inhibitory phosphorylation of eNOS (Thr495) and ameliorates age-related endothelial dysfunction." (PMID 24612481, 2014). "In summary, we demonstrated that GLO1 reduces age-related glycative and oxidative stress in the vasculature and attenuates endothelial dysfunction, concomitant with eNOS activation due to reduced age-related phosphorylation/dephosphorylation of eNOS from early aging." (PMID 24612481, 2014). "For example, high-Glc exposed Glo1-knockdown human aortic endothelial cells (HAECs) have shown an increase in MGO, followed by the upregulation of inflammatory processes, endothelial dysfunction, and disturbances in ECM components." (PMID 38067472, 2023). "By suppressing HK-2 expression and increasing Glo1 expression, tRES-HESP cuts off the drivers of endothelial dysfunction in high glucose concentration at source." (PMID 31133647, 2019). "Moreover, systemic Glo1 over-expression in rats prevents age-related impairment of endothelium-dependent vasorelaxation through modulation of eNOS phosphorylation, proving that blunting glycative stress prevents the long-term impact of endothelial dysfunction on vascular ageing." (PMID 28106778, 2017). "GLO1, the major enzyme detoxifying methylglyoxal (MGO) and the subsequent advanced glycation end products of AGEs, protects vessels from atherosclerosis by inhibiting endothelial dysfunction and smooth muscle proliferation." (PMID 40138913, 2025).
depression (15 papers, 2012 to 2025). "Corroborating findings from post-mortem brain samples would significantly strengthen the association between GLO1 expression and depression." (PMID 23181072, 2012). "Specifically, decreased anxiety-like behavior, decreased depression-like behavior, decreased ethanol consumption, and decreased susceptibility to pilocarpine- and picrotoxin-induced seizures have all been seen following GLO1 inhibitor treatment." (PMID 33478138, 2021). "Although we do not want to extend the discussion at this point, it might also be of interest to examine the relationship between Glo1 and depression-like behavior in future, since our association study of CD-1 mice showed promising results in the TST (CNV No. 680)." (PMID 26011321, 2015). "Alpha-carbonyl aldehydes and their detoxifying enzyme glyoxalase 1 (Glo-1) play vital roles in the pathogenesis of diabetic complications, including depression." (PMID 32982741, 2020). "This supports the notion that a reduced GR function, and thus a reduced expression of GR target genes like Glo1, is involved in the pathogenesis of depression, and that antidepressant treatment is able to restore this dysfunction." (PMID 23384232, 2013). "GLO1 mRNA expression did not significantly differ between patients in remission and healthy controls, suggesting that reduced GLO1 expression was a state-dependent marker for depression." (PMID 23181072, 2012). "GLO1 mRNA expression was reduced in peripheral white blood cells (WBC) of patients with major depressive and bipolar disorders." (PMID 23181072, 2012). "For instance, it is possible that GLO1 regulates depression through its role in modulating GABAergic tone, given evidence that deficits in the GABA system have been implicated in depression." (PMID 23181072, 2012). "A genome-wide meta-analysis demonstrated the association between an SNV in the GLO1 gene and major depression disorder in males, but there was no genome-wide significance." (PMID 34953453, 2022). "In addition, rodent models of depression induced by chronic mild stress and social defeat stress showed depression-like behaviors with decreased GLO1 expression in the brain." (PMID 34953453, 2022). "This indicated that Glo1 expression level was inversely proportional to the severity score on the Hamilton Depression Rating Scale, suggesting that decreased GLO1 expression might be related to pathophysiology of depression disorder." (PMID 34953453, 2022). "MG formation and decreased Glo-1 function play crucial roles in the metabolism of chronic hyperglycemia; therefore, the induction or enhancement of Glo-1 is considered to be an important strategy for the prevention and treatment of common diabetic complications, such as depression." (PMID 32982741, 2020). "Thus, GLO1 inhibitors may be effective as novel and fast-acting drugs for treating depression." (PMID 34953453, 2022). "We believe that it is also necessary to consider the possibility that the administration of GLO1 inhibitors improved depression-like behavior without the pharmacological effects of MG." (PMID 34953453, 2022). "A number of individual top biomarkers are known to be modulated by medications in current clinical use for treating depression, such as by lithium (NRG1, PRPS1, CD47), antidepressants (SLC6A4, DOCK10, NRG1, CD47) and the nutraceutical omega-3 fatty acids (GLO1, SLC6A4, CD47, GLS, HNRNPDL)." (PMID 33828235, 2021). "The docking results of GABRA1 with naringenin and hesperidin, HCRTR1 with naringenin-7-O-glucoside, poncirenin and genipin 1-gentiobioside, and luteolin with SLC6A4, GLO1, MAOB and MTNR1A may clarify the mechanism of action of ZZHPD in treating insomnia and depression." (PMID 35095537, 2021). "However, there is no report on whether hesperidin can improve depression in diabetes via the enhancement of Glo-1 function and the activation of the Nrf2/ARE signaling pathway." (PMID 32982741, 2020).
prostate carcinoma (15 papers, 2010 to 2025). A carcinoma that arises from epithelial cells of the prostate gland. "In this study, we have evaluated GLO1 expression by immunohistochemistry in a tissue microarray cohort consisting of 882 prostate cancer specimens obtained from 187 cases with associated clinical data." (PMID 34298821, 2021). "Elevated expression of Glo1 is associated with gastric cancer, breast sarcoma, ovarian cancer, prostate carcinoma, and hepatocellular carcinoma." (PMID 33396745, 2020). "Genotype and allele frequencies of GLO1 −419C>A polymorphism among prostate cancer (PCa) cases and benign prostatic hyperplasia (BPH) or healthy controls and the associations with the risk of Pca." (PMID 24040147, 2013). "Association between GLO1 −419C>A polymorphism and metabolite levels in prostate cancer progression evaluated by stage and grade." (PMID 24040147, 2013). "In order to study the association of GLO1 A111E polymorphism with oxidative stress, we, firstly, studied GLO1 genotypes and enzymatic specific activity in two differently aggressive and invasive human prostate cancer cell lines." (PMID 24040147, 2013). "Association between GLO1 −419C>A genotypes and prostate cancer (PCa) survival in selected subgroups by tumor stage and grade." (PMID 24040147, 2013). "Association between GLO1 −419C>A polymorphism and the progression of prostate cancer (PCa) evaluated by stage and grade." (PMID 24040147, 2013). "A direct correlation between GLO-1 and PD-L1 expression levels has been confirmed in tissue samples obtained from patients with prostate cancer." (PMID 40727469, 2025). "We previously demonstrated in PC3 human prostate cancer (PCa) cells that the PTEN/PKM2/ERα axis promotes their aggressive phenotype by regulating the Glo1/MG-H1 pathway." (PMID 41009024, 2025). "Prior clinical evidence has documented GLO1 upregulation in various tumor types including prostate cancer (PCa)." (PMID 34298821, 2021). "Previous reports have shown upregulation of GLO1 in various cancers including melanoma, breast cancer, prostate cancer, gastric cancer, pancreatic cancer and renal carcinoma (clear cell carcinoma)." (PMID 34298821, 2021). "We also discuss the promise and challenges for Glo1 inhibitors as future anti-prostate cancer (PCa) therapeutics and the potential of glyoxalases as biomarkers for PCa diagnosis." (PMID 29385039, 2018). "Nuclear GLO1 staining was already reported for human cutaneous basal cell carcinoma and prostate cancer, and nuclear GLO1 translocation was shown in a cell culture model of murine fibrosarcoma." (PMID 28549423, 2017). "Glo1 expression was assessed by immunohistochemistry in paraffin-embedded sections from 60 patients who had undergone radical prostatectomy for either localized (T2) or locally advanced (T3) prostate cancer (PCa)." (PMID 41009024, 2025). "Thus, Glo1 represents a novel actor in the scene of mPCa immunosuppressive tumor microenvironment and a novel player in the process of metastatic prostate cancer immunosurveillance escape." (PMID 34199263, 2021). "Moreover, GLO1 upregulation appears to be a feature of prostate cancers characterized by ERG fusion and PTEN deletion." (PMID 34298821, 2021). "Interestingly, a mechanistic role of GLO1 expression in cancer cell EMT has been suggested before; specifically, it has been demonstrated that GLO1 sustains the metastatic phenotype of prostate cancer cells via EMT control." (PMID 32466621, 2020). "High GLO1 expression was also reported to be closely related to a series of tumors, such as hepatocellular carcinoma 30, 31, gastric cancer 32, cutaneous neoplasms 33, and prostate cancer." (PMID 28170200, 2017). "In the context of prostate cancer, a positive correlation between GLO-1 expression levels and both pathological grade and proliferation rate has been reported, suggesting that GLO-1 may function as a risk factor for prostate cancer growth and disease progression." (PMID 40727469, 2025).
prostate carcinoma (continued). "Indeed, GLO1 gene amplification and elevated expression is a common feature in the progression of multiple human malignancies, including gastric cancer, colorectal cancer, breast cancer, liver cancer, skin tumors, and prostate cancer." (PMID 28549423, 2017). "In prostate cancer, phosphatase and tensin homologue/phosphoinositide 3-kinase (PI3K)/protein kinase B (AKT)/mammalian target of rapamycin signaling regulates both Glo1 and Glo2 expression." (PMID 33396745, 2020). "Moreover, increased circulating levels of Glo1 have also been found in patients with metastatic compared to non-metastatic prostate cancer." (PMID 33869040, 2021). "Furthermore, a growing body of experimental evidence indicates a potential role for GLO1 in tumor cell motility and invasion, which was demonstrated by ectopic GLO1 overexpression or gene silencing in established tumor cell lines derived from gastric cancer, cutaneous SCC, and prostate cancer." (PMID 28549423, 2017).
Insulin resistance (14 papers, 2016 to 2025). Increased resistance towards insulin, that is, diminished effectiveness of insulin in reducing blood glucose levels. "Recent work from our lab indicates that dysregulation of GLO1 in skeletal muscle may underlie human insulin resistance and that exercise training may impart therapeutic benefits." (PMID 30250846, 2018). "The observed inverse correlation between liver Glo1 activity and markers of insulin resistance and liver triglycerides suggests a potential prognostic value of Glo1 activity in early fatty liver disease detection." (PMID 38668337, 2024). "Protein glycation by MG increases with aging likely as a consequence of increased MG formation in age-related insulin resistance and dysglycemia, and decreased MG metabolism by decline of Glo1 activity in aging." (PMID 36521306, 2023). "Several studies have proven the relationship between prednisolone and glucose homeostasis, particularly gluconeogenesis and insulin resistance, but the essential glycolysis-related protein, GLO1, was found in the present study." (PMID 31968011, 2020). "A cross-sectional study of obese subjects have shown a direct correlation of serum AGEs (sAGEs) with markers of inflammation and insulin resistance, and an inverse correlation between sAGEs with innate defenses (e.g. Glo1)." (PMID 31331077, 2019). "Additional research is warranted to determine the physiologic impact of targeting skeletal muscle GLO1 and dicarbonyl stress for the prevention and treatment of skeletal muscle insulin resistance and T2DM." (PMID 30250846, 2018). "Both in vitro and pre-clinical models suggest dicarbonyl stress per se induces insulin resistance and is prevented by GLO1 overexpression, implicating a potential role for GLO1 therapy in insulin resistance and type 2 diabetes (T2DM)." (PMID 30250846, 2018). "Further, in vitro, pre-clinical evidence shows GLO1 overexpression protects against insulin resistance and T2DM." (PMID 30250846, 2018). "This minireview will summarize the existing human literature examining skeletal muscle GLO1 and highlight the emerging therapeutic concepts for GLO1 gain-of-function in conditions such as insulin resistance and cardiometabolic disease." (PMID 30250846, 2018). "We found an enrichment of genes involved in insulin resistance, insulin-like growth factor binding protein complex, monocarboxylic acid metabolic process, which is consistent with the glucose intolerance phenotype in Glo1+/− female mice." (PMID 39896461, 2025). "The induction of Glo1 in overweight and obese subjects through the dietary supplement combination of trans-resveratrol and hesperetin has been reported to counter the accumulation of methylglyoxal, while also reversing insulin resistance and improving dysglycemia and low-grade inflammation." (PMID 38668337, 2024). "Glo1 positively correlates with glucose disposal and negatively with carbonyl stress and HOMA-IR (HOmeostatic Model Assessment for Insulin Resistance)." (PMID 31331077, 2019). "Although GLO1 is highly expressed in skeletal muscle tissue in humans, information on GLO1 protein expression and activity as it pertains to insulin resistance and T2DM is lacking." (PMID 30250846, 2018). "However, under pathological conditions like insulin resistance and T2DM, GLO1 is reduced while MG generation is increased, creating an environment in which dicarbonyl stress persists." (PMID 30250846, 2018). "Finally, treatment of overweight and obese subjects with a dietary supplement inducing increased expression of Glo1 and decreased MG and MG-related AGE formation, producing improved metabolic health - including correction of insulin resistance and improvement of dysglycemia." (PMID 36521306, 2023).
Insulin resistance (continued). "The first clinical trial with the Glo1 inducer, trans-resveratrol and hesperetin combination (tRES-HESP)—a randomized, double-blind, placebo-controlled crossover phase 2A study for correction of insulin resistance in overweight and obese subjects, was completed successfully." (PMID 35269594, 2022).
Nephropathy (14 papers, 2014 to 2025). A nonspecific term referring to disease or damage of the kidneys. "In addition, Glo1 knockout mice were susceptible to acetaminophen-induced hepatotoxicity; Glo1 knockdown mice had a diabetic-nephropathy-like phenotype, while the manipulation of GLO1 activity did not alter the atherosclerotic burden in atherosclerosis-prone Apoe-/- mice." (PMID 40722867, 2025). "In line with this, the manipulation of intracellular MGO formation, by overexpressing Glo1, reduced diabetic retinopathy and nephropathy in rats." (PMID 40722867, 2025). "The important role of GLO-1 in MG clearance are also been suggested in diabetic encephalopathy and nephropathy models of animal." (PMID 31208152, 2019). "Specifically, dicarbonyl stress significantly accelerates kidney aging, as well as kidney disease, and GLO1 has an important renoprotective effect." (PMID 29783710, 2018). "This is while some AGEs, like MG-H1 and Glo1 might also have a role in the development of kidney disease." (PMID 36346460, 2023). "Some studies showed that overexpression of Glo1 in transgenic rats and mice could prevent the development of nephropathy, retinopathy, and neuropathy." (PMID 33143048, 2020). "Likewise, we believed that knockdown of GLO1 would lead not only to kidney disease as we have previously shown but also increase atherosclerosis in nondiabetic Apoe−/− mice." (PMID 24920125, 2014). "CSS promotes atherosclerosis and nephropathy in this study due to increased free radical formation, inflammation, and LDL gly-oxidation products and decreased Glo-1 activity." (PMID 40584440, 2025). "Because MGO-induced oxidative stress is one of the major contributors to diabetic complications, increasing the expression of ROS-related proteins, such as Nrf2/Glo-1/ARE, is a promising strategy for alleviating/preventing AGE-induced nephropathy." (PMID 36978839, 2023). "In contrast to nephropathy, however, we now show that manipulation of GLO1 activity and as a consequence, dicarbonyl stress, does not alter the course of aortic atherogenesis in chow‐fed Apoe−/− mice." (PMID 24920125, 2014). "Thus, manipulation of GLO1 activity does not affect the development of early aortic atherosclerosis in Apoe−/− mice but can dictate the onset of kidney disease independently of blood glucose levels." (PMID 24920125, 2014).